FGFR1 (fibroblast growth factor receptor 1)
Diseases named in the same sentence as FGFR1 in open-access papers (continued):
Sharing a sentence is not in itself a finding about the gene and the disease.
breast cancer (continued). "Furthermore, FGFR1 signaling was shown to contribute to the survival of a breast cancer cell line, indicating FGFR1 as potential therapeutic target." (PMID 22899908, 2012). "Furthermore, there have been few studies comparing amplification of FGFR1 in pure DCIS, DCIS associated with invasive cancer, and invasive breast cancer, although it has been found to be associated with breast cancer progression." (PMID 22863309, 2012). "Since FGFR1 copy number gain and amplification seems to be common in male breast cancer and is suitable for targeted therapy, this gene could be of further interest in male breast cancer." (PMID 22527098, 2012). "Our aim was to clarify the roles of FGFR1–3 in breast cancer cell growth in vitro and in vivo." (PMID 23185502, 2012). "In addition, FGFR1 amplification was found to be associated with decreased disease-free survival, suggesting a role for FGFR1 amplification in the progression of breast cancer including the in situ to invasive transition." (PMID 22863309, 2012). "In breast cancer, amplification and/or overexpression of FGFR1, FGFR2 and FGFR4 have been found." (PMID 23185502, 2012). "Interestingly, they showed a similar response to FGF-8b as S115 cells, suggesting that FGF-8b can upregulate FGFR1 in different types of breast cancer cells." (PMID 23185502, 2012). "Although FGFR1 amplification has been shown to be associated with breast cancer progression, there have been no studies of its association with the in situ to invasive transition." (PMID 22863309, 2012). "In the era of tailored therapies, patients affected by the lobular subtype of breast carcinoma with FGFR-1 amplification could be approached to the new target biological therapy such as FGFR-1 inhibitor, with promising clinical efficacy." (PMID 23270564, 2012). "Amplification of FGFR1 has been reported in breast cancers and relapsed-PC, which may provide a mechanism for the upregulation seen here." (PMID 21952621, 2011). "Among the altered genes, ARHGAP26 and MLLT1 have been associated with leukemia-specific translocations, DDHD2, FGFR1 and PTPN1 have tumor-promoting potential in breast cancer, and CTNNA3 may promote tumor formation in urothelial cancer." (PMID 20428235, 2010). "Moreover, abnormally high levels of Fgfr1 gene expression have been observed in prostate, colorectal, bladder, and a subset of breast carcinomas." (PMID 20405041, 2010). "Based on the increased expression of IL-1β following FGFR1 activation and the link between IL-1β and breast cancer, we hypothesised that IL-1β may be an important factor in the formation of iFGFR1-induced proliferative lesions." (PMID 19393083, 2009). "FGFR1 is amplified in approximately 8 to 10% of human breast cancers." (PMID 19393083, 2009). "Furthermore, we have also determined in vitro that FGFR1 signalling is paramount for the survival of a FGFR1 amplified breast cancer cell line." (PMID 17397528, 2007). "Breast cancer cells, however, appear to contain only the 115-kDa form of FGFR-1." (PMID 9400937, 1997). "This form of FGFR-1 appears to be lost in all breast cancer cells analysed and its absence may have a bearing on malignancy." (PMID 9400937, 1997). "Subsequently, we will attempt to conduct further studies using a larger cohort of patients with breast cancer to elucidate the association of FGFR1 and KLHL6 or other novel gene mutations with acute radiation skin reactions and consider the potential confounding effects of clinical factors." (PMID 38380359, 2024). "Thus, CAPE suppressed breast cancer metastasis through inactivation of FGFR1 via MD2." (PMID 37490511, 2023). "However, it remains unclear whether the FGFR1 signaling pathway can promote breast cancer growth by regulating FOXQ1 expression." (PMID 36778115, 2023). "Therefore, the fine regulation of FGFR1 localization-dependent signalling may be a crucial factor contributing to the aggressiveness of breast cancer." (PMID 35193394, 2022).
breast cancer (continued). "Interestingly, FGFR1 amplification may be breast cancer subtype-specific: in particular, the FGFR1 locus (8q12) is amplified in nearly 15% of hormone receptor-positive breast cancers but only in 5% of triple-negative breast cancers (TNBC)." (PMID 35846378, 2022). "Moreover, amplification of FGFR1 was found in approximately 10% of breast cancers." (PMID 35884601, 2022). "However, their overexpression is mainly found ingastrointestinal cancer, opposite to lung and breast cancers for FGFR1.The efficiency of R4Fu-Q65R-MMAE in vivo suggests the legitimacy oftesting peptibodyC19-PEG4MMAE in animal models to furthercharacterize its potential for anticancer treatment." (PMID 35389227, 2022). "However, the incidence and prognostic role of FGFR1 mRNA overexpression in breast cancer was previously unknown." (PMID 33579347, 2021). "Moreover, FGFR1 and/or FGF3 gene amplification is associated with resistance to HER2 targeted therapy, a shorter PFS survival and a lower pathological complete response (CR) in HER2 (+) early breast cancer treated with neoadjuvant anti‐HER2 therapy." (PMID 33655556, 2021). "Given that SRp55 is commonly mutated in breast and colorectal cancers, and influences the alternative splicing patterns of several tumor-associated genes like KIT, CD44, and FGFR1, it is not surprising that SRp55 depletion decreased the invasion of breast cancer cells." (PMID 32756405, 2020). "In addition to FGFR1, fibroblast growth factor receptor 2 (FGFR2 gene, chromosome 10) and fibroblast growth factor receptor 3 (FGFR3 gene, chromosome 4) belong to the same family of receptor tyrosine kinases and are linked to breast cancer susceptibility." (PMID 32852708, 2020). "Notably, 1/3 of FGFR1-amplified tumors harbor amplification of CCND1 in breast cancer." (PMID 32380883, 2020). "Moreover, using small-interfering molecules against FGFR1 in SU5402 cell line, the authors demonstrated that FGFR1 inhibitor could block breast cancer survival of ductal breast adenocarcinoma cell line MDA-MB-134." (PMID 32188012, 2020). "Moreover, on the basis of the present data GPER may be included among the transduction mechanisms involved in the FGF2/FGFR1 paracrine activation that may contribute to breast cancer development." (PMID 30866584, 2019). "In addition, focusing on the FGF2/FGFR1 functional interaction that occurs between CAFs and breast cancer cells, we determined that FGF2 secretion by estrogens-treated CAFs prompts the up-regulation of CTGF expression through the FGFR1-ERK1/2-AKT signaling cascade in MDA-MB-231 cells." (PMID 30866584, 2019). "Also, FGFR1 activity is required for the survival of an FGFR1-amplified breast cancer cell line." (PMID 27911271, 2017). "The prognostic impact of FGFR1 amplification in breast cancer still remains unclear." (PMID 17397528, 2007). "In patients with breast cancer, HER2 was detected in 39% (65/168), FGFR1 was detected in 32% (19/60), ER was detected in 26% (44/168), and PR was detected in 4% (5/120)." (PMID 40075672, 2025). "In the patients with breast cancer, HER2 was detected in 39% (65/168), FGFR1 was detected in 32% (19/60), ER was detected in 26% (44/168), and PR was detected in 4% (5/120)." (PMID 40075672, 2025). "FGFR1, a receptor tyrosine kinase (RTK), is critical for normal mammary gland development and breast cancer pathogenesis." (PMID 40510030, 2025). "The gene amplification in FGFR1 has been shown to confer resistance to CDK4/6 inhibitor + letrozole and leads to a poor prognosis in patients with ER+ breast cancer." (PMID 40227585, 2025). "This correlates with the co-occurrence of FGFR1 amplification and altered PIK3CA gene activity in breast cancer." (PMID 40135140, 2024). "This review explores the structure, signaling pathways, and implications of FGFRs, particularly FGFR1, FGFR2, FGFR3, and FGFR4, in ER+ breast cancer." (PMID 39040443, 2024).
breast cancer (continued). "Previous studies have predominantly explored FGF2 as a target within the FGF2/FGFR1 signaling pathway, employing exogenous FGF2 to facilitate breast cancer progression." (PMID 39372951, 2024). "Dovitinib was investigated in combination with fulvestrant in postmenopausal women with hormone receptor (HR)-positive, HER2-negative, FGFR (FGFR1, FGFR2, or FGF3)-amplified breast cancer who progressed on endocrine therapy in a phase II trial." (PMID 38255923, 2024). "PTPRG is involved in the control of FGFR1 activity and influences the sensitivity of sarcoma cells to FGFR kinase inhibitors, and is important for cytostasis in breast cancer." (PMID 39034460, 2024). "Dovitinib (TKI258) is a small molecule inhibitor of fibroblast growth factor receptor 1 (FGFR1), FGFR2, and FGFR3 that has demonstrated cell growth inhibition in FGFR-amplified breast cancer cell lines and xenograft models (HBCx2)." (PMID 38339245, 2024). "Although the FGFR1/MEK/ERK pathway has been shown to promote stemness in both Triple-negative breast cancer (TNBC) cell line MDA-MB-231 and luminal A breast cancer cells, there are other mechanisms that can be considered." (PMID 38553760, 2024). "The results from the analysis of gene expression data from TCGA ER + breast cancer patients using generalized linear models based on also showed a correlation between FGF2, FGFR1 and cell cycle states." (PMID 38553760, 2024). "For example, FGFR1 activation contributes to the epithelial–mesenchymal transition (EMT) and metastasis in breast cancer, as well as the carcinogenesis and EMT of prostate cancer." (PMID 39391879, 2024). "Higher frequencies of FGFR1 amplification were also observed in luminal B-like tumors, ER+, HER2-negative breast cancers as well as in patients >50 years of age." (PMID 37546410, 2023). "FGFR1 activation in the mammary epithelium was shown to stimulate proliferation and upregulate epithelial-to-mesenchymal transition (EMT) in a HER2+ breast cancer model." (PMID 37546410, 2023). "In this study, we demonstrated that activation of the FGFR1 signaling robustly upregulated FOXQ1 mRNA and protein expression in breast cancer cells." (PMID 36778115, 2023). "Although FGFR1 and FGFR2 fusions were less frequent overall, FGFR1 was relatively common in breast cancer (0.4%) and FGFR2 in hepatobiliary/hepatocellular cancer (4.3%)." (PMID 37537783, 2023). "HER2-zero breast cancer was found to have gains in 08q24.21 (MYC) and 08p11.23 (FGFR1, ADGRA2, ZNF703)." (PMID 37264417, 2023). "Fibroblast growth factor receptor 1 (FGFR1) is a member of receptor tyrosine kinase (RTK) family and can play an important role in the carcinogenesis and tumor metastasis of breast cancer." (PMID 37490511, 2023). "The greatest functional evidence supporting this mechanism of activation comes from adult cancers, including FGFR1-amplified lung cancer and FGFR1- and FGFR2-amplified breast cancer." (PMID 37130917, 2023). "This study illustrated that CAPE restrained FGFR1 activation and nuclear transfer through MD2/FGFR1 complex inhibition and showed good inhibitory effects on the metastasis of breast cancer cells." (PMID 37490511, 2023). "In breast cancers, the most prevalent fusion genes were FGFR family genes (total, 0.48%; FGFR2, 0.34%; FGFR1, 0.14%), ErbB family genes (total, 0.47%; EGFR, 0.20%; ERBB2, 0.27%), ALK (0.27%) and ROS1 (0.07%)." (PMID 36369474, 2022). "As the canonical FGF8 receptors FGFR2c and FGFR3c are expressed at low level in breast cancer cells, it is possible that FGF8 acts in an autocrine manner on FGFR1 and FGFR4, which are instead present in the breast epithelium." (PMID 35193394, 2022). "It directly binds to TfR1, causing iron deprivation and ROS imbalance with degradations of several oncoproteins, especially FGFR1, through the proteasome pathway, thereby promoting cell apoptosis in MDA-MB-231 breast cancer cells." (PMID 35624697, 2022).
breast cancer (continued). "FGFR1 fusions are typically found in gastrointestinal stromal tumor (GIST), breast cancer, and bladder urothelial carcinoma." (PMID 35402233, 2022). "FGFR1 amplification is frequent in Sq-NSCLC (4.6–22%) and in breast cancer (5–15%), but is less common in other cancer types such as ovarian (5%) and colorectal (2%) carcinomas." (PMID 35402233, 2022). "As with M-CSF, breast cancer cells also produce FGFs, including FGF-21, as well as expressing the FGFR1, thereby enabling autocrine tumor cell proliferation." (PMID 35677046, 2022). "For example, poor response to CDK4/6 inhibitors has been observed in patients with coexisting FGFR1 amplification in hormone receptor-positive breast cancer and dual HER2-targeted therapy in HER2-positive breast cancer." (PMID 35193394, 2022). "FGFR1 amplification activates of the PI3K/AKT and RAS/MEK/ERK signaling pathways, specifically in endocrine-resistant breast cancer cells." (PMID 36358806, 2022). "In breast cancer, FGF2 mRNA expression positively correlates with CAF abundance, and siRNA silencing of FGFR1 in MDA-MB-231 breast cancer cells co-implanted with FGF2+ CAFs significantly reduced xenograft tumor burden." (PMID 36671452, 2022). "NRP1 forms a complex with FGFR1 in the cytoplasm, which increases during EMT in HER2+ drug-resistant breast cancer cells." (PMID 34068954, 2021). "In HER2-positive breast cancer cells with EMT, resistance to HER2 inhibitor was mediated by increased expression and direct interaction of FGFR1 and neuropilin-1 (NRP1)." (PMID 34830951, 2021). "Combined exposures to AZD4547 (FGFR1 inhibitor) and GANT61 (GLI1 inhibitor) significantly reduced cell proliferation, cell motility, and invasion, suggesting molecular crosstalk in breast cancer progression and metastasis." (PMID 34722544, 2021). "Other studies showed that amplification of FGFR1, FGFR2, or FGFR3 in ER-positive human breast cancers correlates with concomitant resistance to estrogen-related therapy." (PMID 34830951, 2021). "Taken together, our data suggest that HR+ breast cancer cell lines with elevated FGFR1 levels (either because of amplification or increased mRNA levels) require the combination of ER, CDK4/6 and FGFR1 blockade for maximum cell cycle arrest." (PMID 33579347, 2021). "We also demonstrated that simultaneous targeting of FGFR1 and GLI1 using GANT61 and AZD4547 inhibitors significantly decreases breast cancer invasion and metastasis, suggesting new approaches for clinical studies." (PMID 34722544, 2021). "The FGFR1 and FGFR3 inhibitor BGJ398 was investigated in a phase II clinical trial for FGFR1-amplified lung cancer and FGFR1/2-amplified and FGFR3-mutant breast cancer." (PMID 34639155, 2021). "Herein, we reported a different mechanism by which coexpression of FGFR1 and GLI1 genes leads to breast cancer invasion and metastasis." (PMID 34722544, 2021). "Overall, since breast cancer patients resistant to CDK4/6 inhibitors can gain resistance due to an FGFR1 amplification, the same therapeutic effect of FGFR1 inhibition will likely be seen if a future study focuses on this specific population." (PMID 34830174, 2021). "FGFR1 and CCND1 CN alterations were more common in HR + HER2- breast cancer (q = 0.01 and q < 0.001, respectively)." (PMID 33893289, 2021). "In breast cancer cells, FGFR activation-dependent cleavage of FGFR1 generates a C-terminal fragment that can translocate to the nucleus and control the expression of target genes." (PMID 34830836, 2021).
breast cancer (continued). "Increased FGFR1 and FGF3 expression was correlated with a poor response to anti-HER2 treatment in breast cancer patients, and this was overcome using a combination therapy of FGFR inhibitors together with lapatinib and trastuzumab." (PMID 34830836, 2021). "Examples of FGFR1 fusion partners are HOOK3 in gastrointestinal stromal tumour, TACC1 in glioblastoma and ZNF703 in breast cancer." (PMID 34830836, 2021). "Particularly, FGFR1 and GLI1 showed strong correlation with late stage, node, and metastasis in luminal subtypes of breast cancer patients." (PMID 34722544, 2021). "The FGFR1–3 inhibitor named AZD4547 was tested in a phase II clinical trial in patients with advanced tumors, including HER2-negative breast cancer, non-small cell lung cancer, and gastroesophageal carcinomas harboring FGFR1/2 amplification." (PMID 33081025, 2020). "The aim of this study was to investigate the amplification rates of FGFR1, FGFR2, and FGFR3 in patients with breast cancer and their impact on prognosis." (PMID 32852708, 2020). "Recently, estrogens have been shown to mediate FGF2/FGFR1 paracrine activation through the G protein estrogen receptor (GPER), which coupled CAFs to breast cancer cells towards migratory and invasive tumor cell responses." (PMID 33081025, 2020). "Moreover, CCND1 may mediate FGFR1-induced drug resistance in ER+ breast cancer." (PMID 32380883, 2020). "Frequently affected genes by CNVs in Chinese breast cancer patients were ERBB2 (25%), MIEN1 (25%), GRB7 (24%), TRPS1 (6%), MYC (6%), ERLIN2 (6%), PLPP5 (6%), NSD3 (6%), FGFR1 (6%), and CCND1 (5%)." (PMID 33173047, 2020). "This study investigated the amplification rates of the fibroblast growth factor receptor genes FGFR1, FGFR2, and FGFR3 in patients with breast cancer." (PMID 32852708, 2020). "MiR-361-5p inhibits the glycolysis and invasion of breast cancer cells by respectively targeting MMP-1 and fibroblast growth factor receptor 1 (FGFR1), which is a promoter of glycolytic enzyme and a suppresser of OXPHOS (oxidative phosphorylation)." (PMID 32547948, 2020). "In this vein, the amplification of the FGFR1 and FGFR2 gene loci has been described as recurrent in this breast cancer subtype." (PMID 33081025, 2020). "While the roles of FGFR1 and FGFR2 in breast cancer have been studied in considerable detail, FGFR3 remains poorly characterized in this setting." (PMID 31987043, 2020). "Various aberrations in the fibroblast growth factor receptor genes FGFR1, FGFR2, and FGFR3 are found in different cancers, including breast cancer (BC)." (PMID 32852708, 2020). "Overexpression of fibroblast growth factor receptor 1 (FGFR1) is a common aberration in lung and breast cancers and has necessitated the design of drugs targeting FGFR1‐dependent downstream signaling and FGFR1 ligand binding." (PMID 30968602, 2019). "In this study, we found that Fibroblast growth factor receptor 1 (FGFR1), which is amplified in lung and breast cancer, was downregulated in bladder cancer samples compared with that of the controls." (PMID 31293967, 2019). "FGFR1 amplification, for instance, occurs in non-small cell lung cancer (NSCLC) and breast cancer patients." (PMID 31527449, 2019). "For example, ERBB2 amplification and fibroblast growth factor receptor 1 gene (FGFR1) amplification are drivers of therapeutic resistance and poor prognosis in ER+ breast cancer." (PMID 31106278, 2019). "Based on these results, we propose FGFR1 inhibitors in combination with ER and CDK4/6 antagonists as a testable therapeutic strategy in ER+ breast cancers also harboring aberrant FGFR signaling as a result of FGFR pathway gene alterations." (PMID 30914635, 2019).